ARHGAP28 (Rho GTPase activating protein 28)
Description:
GTPase activator for the Rho-type GTPases by converting them to an inactive GDP-bound state.
Synonyms: KIAA1314; FLJ10312
Tractability: PROTAC: ubiquitination databases record sites on it; its protein half-life has been measured.
Safety:
Unwanted effects reported when the protein is acted on. In parentheses: how it was acted on, where the effect was seen, and who reports it.
Pegaspargase Hypersensitivity (source: ClinPGx)
Gene: Protein-coding gene on chromosome 18 (6,729,680 to 6,915,716, forward strand). Ensembl gene ENSG00000088756.
Subcellular location (Human Protein Atlas): Cell Junctions; Nucleoplasm
Pathways (Reactome):
Signal Transduction: RHOA GTPase cycle
Gene Ontology:
Molecular function: GTPase activator activity
Biological process: negative regulation of stress fiber assembly; regulation of actin filament polymerization; regulation of small GTPase mediated signal transduction; signal transduction
Cellular component: cytoplasm; cytosol
Genetic constraint (gnomAD): Loss-of-function variants: 48 observed, 76.71 expected, observed/expected ratio (o/e) 0.63, 90% interval 0.5 to 0.8. The upper end of that interval is the gene's LOEUF score, 0.8, which puts it in group 3 of 6, group 1 being the genes least tolerant of losing a copy. Missense variants: 798 observed, 839.68 expected, observed/expected ratio (o/e) 0.95, 90% interval 0.9 to 1.01. Synonymous variants: 288 observed, 300.68 expected, observed/expected ratio (o/e) 0.96, 90% interval 0.87 to 1.06.
Homologues: Orthologues: chimpanzee ARHGAP28 (99% identical), macaque ARHGAP28 (93% identical), dog ARHGAP28 (89% identical), pig ARHGAP28 (89% identical), rabbit ARHGAP28 (88% identical), rat Arhgap28 (85% identical), mouse Arhgap28 (85% identical), guinea pig ARHGAP28 (82% identical), tropical clawed frog arhgap28 (22% identical), zebrafish arhgap28 (21% identical), Drosophila melanogaster conu (18% identical). Paralogues in human: ARHGAP18 (40% identical), ARHGAP40 (31% identical), ARHGAP19 (12% identical).
Diseases named in the same sentence as ARHGAP28 in open-access papers:
ARHGAP28 is named in the same sentence as 21 diseases in open-access papers, as found by Europe PMC text mining. Sharing a sentence is not in itself a finding about the gene and the disease. The quoted sentences say what the papers report.
meningioma (2 papers, 2019 to 2025). A generally slow growing tumor attached to the dura mater. "In the development of meningiomas, ARHGAP28 plays an important role, particularly in pathways related to cell migration and invasiveness." (PMID 40181839, 2025). "ARHGAP28 has been previously reported in array expression studies as a DEG and, using a platform not included in our meta-analysis, it was found to be upregulated in GII and, with statistical significance, in GIII compared with GI meningiomas." (PMID 31083655, 2019).
migraine (2 papers, 2019 to 2022). "These are associated with a variety of neurological diseases, such as cognitive defects (ARHGAP15), migraine without aura (ARHGAP28), AD (ARHGAP2), schizophrenia (ARHGAP18), and bipolar disorder (BD; ARHGAP29; Niftullayev and Lamarche-Vane, 2019)." (PMID 35783123, 2022).
breast carcinoma (1 paper, 2025). "Additionally, ARHGAP28 is also associated with the recurrence and progression of breast cancer." (PMID 40181839, 2025).
colon cancer (1 paper, 2025). "Research has found that the promoter region of ARHGAP28 exhibits significant methylation in colon cancer cells with high metastatic potential." (PMID 40181839, 2025).
diabetic nephropathy (1 paper, 2025). "The diabetic nephropathy model using db/db mice showed that ARHGAP28 expression was significantly upregulated in the kidney cortex and glomeruli." (PMID 40181839, 2025). "Further analysis of diabetic human kidney glomeruli demonstrated that ARHGAP28 is also highly upregulated in diabetic conditions, suggesting its potential role in the pathogenesis of diabetic nephropathy." (PMID 40181839, 2025).
osteosarcoma (1 paper, 2023). A usually aggressive malignant bone-forming mesenchymal neoplasm, predominantly affecting adolescents and young adults. "We found that overexpression of ARHGAP28 can inhibit the proliferation, migration, and invasion of osteosarcoma cells." (PMID 38041020, 2023). "We injected stable ARHGAP28 overexpressing 143B osteosarcoma cells and NC cells into nude mice subcutaneously." (PMID 38041020, 2023). "High expression of ARHGAP28 in osteosarcoma cell lines can inhibit the proliferation, migration, and invasion of osteosarcoma, and we can judge the risk of OS patients based on this." (PMID 38041020, 2023). "Results of wound healing experiments showed that ARHGAP28 inhibited the migration of human osteosarcoma cell lines." (PMID 38041020, 2023). "In summary, ARHGAP28 may play a positive role in inhibiting the growth and progression of osteosarcoma." (PMID 38041020, 2023). "We found that overexpression of ARHGAP28 inhibited the activity of human osteosarcoma cells." (PMID 38041020, 2023). "The overexpression of ARHGAP28 can inhibit the proliferation, migration, and invasion of osteosarcoma cells and tumor growth in mice, and IHC showed that overexpression of ARHGAP28 could inhibit the proliferation of tumor cells." (PMID 38041020, 2023). "Since the role of ARHGAP28 in osteosarcoma remains unclear, we confirmed the role of ARHGAP28 through in vitro and in vivo biological experiments." (PMID 38041020, 2023). "Finally, we conducted in vivo and in vitro experiments to investigate the effect of ARHGAP28 on osteosarcoma." (PMID 38041020, 2023). "Therefore, we speculate that ARHGAP28 is a tumor suppressor gene for osteosarcoma, and we plan to further study it in the next step." (PMID 38041020, 2023). "In addition, transwell results suggested that ARHGAP28 overexpression could also inhibit the invasion ability of osteosarcoma cell lines." (PMID 38041020, 2023). "Finally, the expression level of ARHGAP28 in osteosarcoma is significantly related to the prognosis and survival time of patients, but it has not been studied in osteosarcoma." (PMID 38041020, 2023).
prostate carcinoma (1 paper, 2024). A carcinoma that arises from epithelial cells of the prostate gland. "In prostate cancer from AA men, genes including known AR target genes TRIM63, ATP2A1, and ARHGAP28, showed a significant inverse correlation between gene expression and DNA methylation." (PMID 38566104, 2024).
renal cell carcinoma (1 paper, 2020). "Lower expression of ARHGAP28 was associated with significantly worsened prognosis in renal cell carcinoma (P = 3.7e-6)." (PMID 33041663, 2020).
tumor (5 papers, 2012 to 2024). "In vivo experiments have shown that overexpression of ARHGAP28 can inhibit tumor growth in mice, and IHC has shown that the reduced level of Ki-67 in the ARHGAP28 overexpression group can inhibit the proliferation of tumor cells." (PMID 38041020, 2023). "Tumor volume was monitored every 7 days, and ARHGAP28 overexpression resulted in smaller tumors compared to NC." (PMID 38041020, 2023). "Remarkably, in the TCGA‐LGG and GTEx cohorts, a significant majority of the ARHGAP family genes, with the exception of ARHGAP15, ARHGAP20, ARHGAP24, and ARHGAP28, exhibited notable differential expression between tumour tissues and normal samples, as established through Wilcoxon test analysis." (PMID 39075640, 2024). "In conclusion, our results indicate that ARHGAP28 overexpression suppresses in vivo tumor growth." (PMID 38041020, 2023). "The deleted 18p11.21 region contains important tumor inhibitory genes, for example EPB41L3, L3MBTL4, ARHGAP28, PTPRM, and ROCK1 (for complete list of genes in deletion regions)." (PMID 22363777, 2012). "In GBM-derived radioresistant tumor-initiating and PROM1-positive cell populations, ARHGAP28 was upregulated upon treatment with the anticancer compound resveratrol that resulted in induction of apoptosis and elevated radiosensitivity through repression of STAT3 pathway signaling." (PMID 31083655, 2019).
cancer (3 papers, 2019 to 2023). A tumor composed of atypical neoplastic, often pleomorphic cells that invade other tissues. "Interestingly, we found that loss of ARHGAP28 located on 18p is associated with cancer-intrinsic sensitivity to Cabozantinib and Sorafenib." (PMID 33041663, 2020).
kidney diseases (1 paper, 2025). "Given its consistent overexpression in both normal and diabetic conditions, ARHGAP28 emerges as a prime candidate for functional assays to explore its role in podocyte biology and its potential as a therapeutic target in kidney diseases." (PMID 40181839, 2025).
ARHGAP28 also shares sentences with these, for which no sentence is quoted: Autoimmunity (1 paper); bipolar disorder (1); cognitive defects (1); migraine without aura (1); neurological diseases (1); pancreatic tumor (1); prostate tumor (1); schizophrenia (1); substance dependence (1); thyroid disease (1).